MPO (myeloperoxidase)
Diseases named in the same sentence as MPO in open-access papers (continued):
Sharing a sentence is not in itself a finding about the gene and the disease.
Cerebral ischemia (36 papers, 2012 to 2026). Restriction of arterial blood supply to the brain associated with insufficient oxygenation to support the metabolic requirements of the tissue. "While myeloperoxidase (MPO) is primarily involved in antimicrobial defense, its activity is closely linked to inflammasome-mediated inflammatory responses including those in brain ischemia injury, and it can also be used to estimate leukocyte recruitment to tissues." (PMID 40284217, 2025). "Cerebral ischemia and edema are frequently associated with neuroinflammation, augmented production of proinflammatory mediators, and infiltration of inflammatory cells (e.g., MPO+ neutrophils and CD68+ monocyte/macrophages)." (PMID 24828425, 2014). "Numerous bioactive compounds have been identified as inhibitors of myeloperoxidase (MPO) activity and can help alleviate cerebral ischemia–reperfusion injury." (PMID 41304923, 2025). "Myeloperoxidase (MPO) plays critical role in the pathology of cerebral ischemia–reperfusion (I/R) injury via producing hypochlorous acid (HOCl) and inducing oxidative modification of proteins." (PMID 38515139, 2024). "Myeloperoxidase (MPO) was a functional and activation marker of neutrophils, a vital marker of inflammatory, and closely related to the inflammatory after cerebral ischemia." (PMID 39302945, 2024). "MPO is a critical inflammatory enzyme and therapeutic target, triggering both oxidative stress and neuroinflammation in the pathological process of cerebral ischemia–reperfusion injury." (PMID 38275657, 2024). "MPO plays an important role in neurodegenerative diseases, including AD, Parkinson’s disease (PD), cerebral ischemia, and multiple sclerosis (MS)." (PMID 38275657, 2024). "Recent studies identified many active compounds with the bioactivities of inhibiting MPO activity, which can be potentially used to attenuate cerebral ischemia-reperfusion injury." (PMID 32508671, 2020). "Myeloperoxidase (MPO) is a critical inflammatory enzyme and therapeutic target triggering both oxidative stress and neuroinflammation in the pathological process of cerebral ischemia-reperfusion injury." (PMID 32508671, 2020). "This article discusses the important roles of MPO in mediating oxidative stress and neuroinflammation during cerebral ischemia-reperfusion injury and reviews the current understanding of the underlying mechanisms." (PMID 32508671, 2020). "In conclusion, MPO plays a vital role in mediating cerebral ischemia-reperfusion injury via mediating oxidative stress and neuroinflammation." (PMID 32508671, 2020). "Treatment with fucoidan (80, 160 mg/kg) inhibited MPO activity and inflammation-associated cytokines such as IL-1, IL-6, TNF-α, and attenuated cerebral ischemia-reperfusion injury." (PMID 32508671, 2020). "Forsythoside B at the dosage of 20 mg/kg attenuated brain infarct size, brain edema, and BBB permeability through inhibiting MPO activity and NF-κB expression against cerebral ischemia/reperfusion injury." (PMID 32508671, 2020). "Among the downregulated proteins in tmTNF expressing microglia was MPO, a reactive oxygen species generating enzyme known to be expressed by leukocytes and to increase in cerebral ischemia." (PMID 31440125, 2019). "As a result, the TTC staining demonstrated that the model of brain ischemia was successfully established, and MPO experiments reported that lung damage was induced in MCAO rats." (PMID 31191213, 2019). "To investigate the effects of FNS on inflammatory reaction in cerebral ischemia/reperfusion, we determined the MPO activity by spectrophotometer method." (PMID 26016630, 2015). "MPO is considered an index of neutrophil infiltration, and highly expressed cerebral ischemia after 24 h." (PMID 23414442, 2013). "In addition, DHQ decreased the activity of myeloperoxidase, brain mRNA levels of interleukins, and Nfkb2 in cerebral ischemia/reperfusion in rats, thus inhibiting inflammation." (PMID 37886968, 2023).
Cerebral ischemia (continued). "Reduction of other inflammatory biomarkers has also been reported following GLP-1RA treatment in rodent models of cerebral ischemia, namely myeloperoxidase, IL-1β, IL-6, IL-18, and cyclooxygenase-2 (COX-2), the latter through increasing expression of islet-brain-1 (IB1)." (PMID 36380358, 2022). "Myeloperoxidase (MPO), a key inflammatory enzyme secreted by activated neutrophils and macrophages/microglia, can generate highly reactive oxygen species to cause additional damage in cerebral ischemia." (PMID 32450881, 2020). "MPO produced from neutrophils has been used as a marker of infiltrating neutrophils and is involved in brain damage following such events as traumatic brain injury and cerebral ischemia." (PMID 22998689, 2012). "Furthermore, we summarize the active compounds from medicinal herbs with potential as MPO inhibitors for anti-oxidative stress and anti-inflammation to attenuate cerebral ischemia-reperfusion injury, and as adjunct therapeutic agents for extending the window of thrombolytic treatment." (PMID 32508671, 2020). "In addition, myeloperoxidase (MPO), a key inflammatory enzyme secreted by activated neutrophils and macrophages/microglia, can generate highly reactive oxygen species to cause additional damage in brain ischemia." (PMID 24634780, 2013). "Following acute cerebral ischemia, BBB damage facilitates substantial neutrophil infiltration into the central nervous system, accompanied by increased MPO production." (PMID 40777988, 2025). "In STZ-induced diabetic rats, liraglutide showed its protective effects on brain nerve cells against cerebral ischemia by activating the Nrf2/HO-1 pathway and promoting the activities of other antioxidant enzymes, including SOD and myeloperoxidase (MPO)." (PMID 38255895, 2024). "Another alakaloid, l-Tetrahydropalmatine, exhibited cardioprotective effects against acute global cerebral ischemia-reperfusion injury by activating the PI3K/Akt/eNOS/NO pathway and decreasing the accumulation of inflammatory factors, such as TNF-α and MPO." (PMID 35888597, 2022). "Then, immunohistochemistry and myeloperoxidase activity assessment were performed to explore the effects of CD151 expression on neutrophil and monocyte recruitment after rat cerebral ischemia." (PMID 34022890, 2021). "To investigate the neutrophil infiltration in the acute phase of cerebral ischemia, we performed DAB staining to detect MPO-positive cells." (PMID 29724240, 2018). "To investigate the effect of metformin on neutrophil infiltration in the acute phase of cerebral ischemia, we performed 3,3’-diaminobenzidine (DAB) staining to detect MPO+ cells." (PMID 25315906, 2014). "In a diabetic rat model of cerebral ischemia–reperfusion, administration of Res at a dose of 20 mg/kg effectively reduced levels of malondialdehyde (MDA), TNF-α, IL-6 and myeloperoxidase (MPO), while increasing levels of catalase (CAT), superoxide dismutase (SOD), and IL-10." (PMID 41601537, 2026). "Previous studies showed that allicin could reduce cerebral infarction areas, neuronal apoptosis, myeloperoxidase (MPO) activity, and tumor necrosis factor (TNF)‐α levels in serum to protect the brain from cerebral ischemia/reperfusion injury." (PMID 37673878, 2023). "To explore whether the neuroprotective effect of kaempferol glycosides is related to the inhibition of neutrophil infiltration after cerebral ischemia-reperfusion, we examined the effects of KRS and KGS on the expression of MPO, a specific neutrophil marker." (PMID 23437066, 2013). "A recent study has found that microglial myeloperoxidase(MPO) -containing exosomes increase HOCl production in neighboring neurons and mediate disulfide HMGB1 translocation, thereby exacerbating neurological deficits in ischemic brain injury and cerebral ischemia/reperfusion injury." (PMID 38740617, 2025).
Cerebral ischemia (continued). "By replicating the rat model of cerebral ischemia, this study explored whether THSWD can reduce cell necrosis and neuroinflammation in the rat model of MCAO by inhibiting the expression levels of MCP-1, IL-1β, IBA-1, and MPO inflammatory factors as well as the TNF-α/RIP1/RIP3/MLKL pathway." (PMID 34447315, 2021).
type 2 diabetes (36 papers, 2014 to 2026). "Serum MPO levels and activities are significantly associated with coronary atherosclerotic plaque progression in patients with type 2 diabetes." (PMID 36404308, 2022). "The prevalence of anti-MPO antibodies in type 1 diabetes has been identified as 38% but is infrequent in type 2 diabetes." (PMID 40177446, 2025). "Nitric oxide synthases (NOS1, NOS2, and NOS3) and myeloperoxidase (MPO), which have been implicated in the development of type 2 diabetes, are also important ROS-generating enzyme families." (PMID 36902173, 2023). "MPO activity products, namely 3-chlorotyrosine and 3-nitrotyrosine were elevated and decreased efflux in Chinese type 2 diabetic patients." (PMID 29505607, 2018). "Plasma levels of cLDL were elevated in patients with type 2 diabetes even with normal renal function and the increased levels of cLDL were correlated with myeloperoxidase." (PMID 27973558, 2016). "Mechanistically, it has been shown that treatment with GLP-1 RA reduced ROS production and recovered mitochondrial membrane potential, mitochondrial respiration, and myeloperoxidase (MPO) levels in persons with type 2 diabetes, in line with our earlier findings regarding mitochondrial metabolomics." (PMID 40277890, 2025). "The multivariate analysis established type 2 diabetes and its correlation with elevated MPO levels." (PMID 36463116, 2022). "In conclusion, patients with type 2 diabetes had increased plasma MPO concentrations." (PMID 26451069, 2015). "Only seven genes had the same direction of effect for comparison of type 2 diabetes samples and healthy samples in all eight datasets: LOC112268118 and MPO had positive logFC, and IL18BP, DELE1, TSPAN32, ITFG2, and NISCH all had negative logFC." (PMID 41465472, 2025). "In insulitic donors with type 2 diabetes, the pancreases were characterised according to the presence of CD68 (macrophages), myeloperoxidase (MPO; neutrophils), CD3, CD20 (B cells) and HLA class I hyperstained islets." (PMID 27796420, 2017). "Supporting this, a clinical cross-sectional study reported significantly higher MPO levels only in individuals with nondiabetic MetS, but not in those with prediabetes or newly diagnosed type 2 diabetes." (PMID 40563378, 2025). "In order to explore in more depth the inflammatory process that occurs in type 2 diabetes, we measured the levels of inflammation markers TNF-α, ICAM-1 and MPO in serum, and compared the leukocyte–endothelium interactions in type 2 diabetic participants with those in healthy participants." (PMID 38981930, 2024). "Therefore, in this study, we determined the relationship between MPO levels and the incidence of CAD in patients with type 2 diabetes." (PMID 26451069, 2015). "The authors compared levels of superoxide dismutase (SOD), malondialdehyde (MDA), myeloperoxidase (MPO), ischemia-modified albumin (IMA), and heat shock protein 70 (HSP70) after reperfusion to percutaneous intervention (PCI) in elderly patients with AMI and type 2 diabetes." (PMID 39334765, 2024). "Plasma MPO level and Gensini score were positively correlated, suggesting that MPO might be an influential factor in the progression of CAD among diabetics and might serve as a new target for the diagnosis and treatment of CAD in patients with type 2 diabetes." (PMID 26451069, 2015). "In particular, a significant increase in serum MPO-DNA complexes (p < 0.0001) was observed in patients with type II diabetes who also have diabetic kidney disease when compared to control subjects (patients with type II diabetes without diabetic kidney disease)." (PMID 39769394, 2024).
influenza (35 papers, 2009 to 2025). An acute viral infection of the respiratory tract, occurring in isolated cases, in epidemics, or in pandemics; it is caused by serologically different strains of viruses (influenzaviruses) designated A, B, and C, has a 3-day incubation period, and usually lasts for 3 to 10 days. "Another mediator of influenza-associated lung injury is myeloperoxidase (MPO), which is predominantly secreted by neutrophils during cases of severely pathogenic influenza infections." (PMID 34691044, 2021). "Furthermore, several studies have proposed that MPO is an independent risk factor for the early prediction of severe influenza." (PMID 39340342, 2024). "Elevated levels of NET production have been observed in plasma from patients with severe influenza infections by measuring cell-free deoxyribonucleic acid (DNA) and myeloperoxidase (MPO)-DNA." (PMID 41346583, 2025). "The nomogram model, based on the expression levels of MPO and HP and the duration of illness, was verified as a reliable prediction model for severe influenza." (PMID 39340342, 2024). "A nomogram based on the expression levels of MPO, HP, and duration of illness is an efficient model for the early identification of patients with severe influenza." (PMID 39340342, 2024). "Regarding antiinfection prophylaxis measures, both subgroups were comparable, 13 (26%) anti-MPO antibody-positive patients were vaccinated against flu and/or S. pneumoniae (4 in the low ceruloplasmin group and 9 in the high ceruloplasmin group)." (PMID 39388433, 2024). "The nomogram for severe influenza, based on the expression levels of MPO and HP and duration of illness, was demonstrated to have good discrimination, calibration, and clinical value." (PMID 39340342, 2024). "Multivariate logistic regression demonstrated significant correlations between severe influenza and myloperoxidase (MPO) level, haptoglobin (HP) level, and duration of illness." (PMID 39340342, 2024). "We identified that the activity of reactive oxygen species (ROS) and the myeloperoxidase (MPO) activity of neutrophils in the lungs played an important role in antibacterial host defense in influenza-infected lungs." (PMID 36475755, 2023). "Lower numbers of infiltrating macrophages, lymphocytes and neutrophils, and myeloperoxidase (MPO) activity, were also found in influenza-infected lungs following administration (intraperitoneal injection) of NAC in mice." (PMID 37891946, 2023). "A study has demonstrated that patients with severe influenza presented with elevated NETs in the plasma, and the neutrophils from these patients released a greater amount of myeloperoxidase-DNA (MPO-DNA) complex in response to IL-8." (PMID 34359859, 2021). "In patients with severe influenza infections, high MPO-DNA complex levels correlate with poor prognosis." (PMID 33717105, 2021). "Again, LPS administration also resulted in increased MPO levels in lung tissue, and there was a trend towards enhanced MPO content in influenza-infected mice challenged with LPS 4 days after infection." (PMID 29978355, 2018). "The LPS-induced increase in MPO content in lung homogenates, reflecting pulmonary neutrophil influx or sequestration, tended to be enhanced in the acute phase of influenza infection as well." (PMID 29978355, 2018). "In accordance with pulmonary cytokine levels, influenza infection by itself led to increased MPO content in the lungs 4 days after infection and tended to result in increased MPO content 10 days post-infection." (PMID 29978355, 2018). "We previously showed that NETs induction during influenza is regulated by MPO activity, with increased MPO activity found in BALF from animals with lethal influenza." (PMID 23467809, 2013). "In contrast, influenza infection alone displayed predominantly continuous staining for histone or MPO." (PMID 23467809, 2013).
influenza (continued). "Aged animals had delayed lung infiltration kinetics following influenza infection; however, similar levels of MPO were produced by adult and aged mice, except for day 9, where higher levels were detected in the aged group (p < 0.05) (data not shown)." (PMID 19922665, 2009). "Moreover, influenza infection can hinder the secretion of granulocyte colony-stimulating factor (G-CSF) and reduce myeloperoxidase (MPO) activity, resulting in dysfunctional neutrophil bacterial clearance." (PMID 40309731, 2025). "Our earlier studies with TG6-44 showed ROS inhibition in MPO-specific manner highlighting the possibility that modulation of MPO in cells could alter the course of host response to influenza infection." (PMID 34280220, 2021). "Also, the increased MPO content observed in our study is an important hallmark of acute respiratory distress syndrome (ARDS), a severe complication of influenza infection caused by excessive pulmonary inflammation." (PMID 29978355, 2018). "Thus, PAR2 appears to induce an anti-influenza defence mechanism in human neutrophils based on degranulation, MPO release and ROS production." (PMID 24171176, 2013). "Myeloperoxidase (MPO) as well as other compounds of azurophil granules were demonstrated to have anti-influenza activity and, thus, may contribute to host protective rather than harmful functions." (PMID 24171176, 2013). "LASSO analysis showed that severe influenza was significantly correlated with duration of illness, age, bacterial status, DEFA3, HP, and MPO." (PMID 39340342, 2024). "In comparison, three patients had high activation of only a subset of influenza-connected genes PRTN3, LTF, PGLYRP1, DEFA1B, DEFA1, DEFA4, ELANE, and MPO." (PMID 34335605, 2021). "Staining specifically for myeloperoxidase (MPO), most abundantly present in the granules of neutrophils, confirmed increased numbers of MPO+ neutrophils in the lung of Ifnar1−/− mice after influenza infection." (PMID 21383977, 2011). "Furthermore, we found that ONP-302 reduced the levels of MPO, albumin, IL-6, and TNF-α in the lungs of aged, influenza-infected mice." (PMID 35737459, 2022). "On the other hand in a mouse model of influenza it was shown that the inflammation damage was reduced by the absence of MPO." (PMID 33079950, 2020). "Plasma of influenza-infected patients showed elevated levels of elastase and MPO but did not test positive for nucleosomes or DNA assessed by PicoGreen®." (PMID 30992428, 2019). "Moreover, we demonstrated that DF derived from PAR2 agonist-activated neutrophils contains MPO and disrupts extracellular IAV, indicating a MPO-dependent anti-influenza action." (PMID 24171176, 2013). "The ten common DEGs (PCOLCE2, HLA_DPA1, LOC653061, TDRD9, MPO, HLA_DQA1, MAOA, S100P, RAP1GAP, and CA1) that were obtained by overlapping genes from computing the three algorithms [LASSO regression, SVM-RFE algorithms, and RF are candidate key genes for severe influenza." (PMID 38454348, 2024). "In contrast, PCOLCE2, TDRD9, MPO, MAOA, RAP1GAP, and S100P expression was higher in the severe influenza group compared to the non-severe influenza group in the training cohort, similar to the findings in the validation cohort." (PMID 38454348, 2024). "Yet, an extremely interesting study that corresponds to ours was found related to influenza, in which it was registered that the level of LZM is inhibited by this virus, whereas simultaneously, the virus does not influence the level of MPO." (PMID 32899838, 2020).